HMOX1 (heme oxygenase 1)
Diseases named in the same sentence as HMOX1 in open-access papers (continued):
Sharing a sentence is not in itself a finding about the gene and the disease.
diabetic cardiomyopathy (30 papers, 2012 to 2026). Diabetic cardiomyopathy is a disorder of the heart muscle in people with diabetes. "In contrast, its liver toxicity is linked to targets like IFNG and HMOX1, mainly through the diabetic cardiomyopathy pathway, potentially increasing risks due to overlapping pathways." (PMID 41155650, 2025). "HMOX1 is significantly upregulated in multiple diseases, such as proliferative diabetic retinopathy and diabetic cardiomyopathy, where it plays a critical role in regulating iron homeostasis and providing cytoprotection." (PMID 41503916, 2026). "HMOX1 expression is upregulated in diabetic myocardial tissues, and knocking down HMOX1 ameliorates ferroptosis, thereby relieving diabetic cardiomyopathy by reducing cardiac fibrosis and improving cardiac function." (PMID 41198625, 2025). "The AMPK/Nrf2/heme oxygenase-1 (HO-1) pathway, an anti-oxidative defense system, was reported to be related to the development of diabetic cardiomyopathy and the restoration of cardiac function." (PMID 32038243, 2019). "In a study on C57BL/6 mice with induced diabetic cardiomyopathy, luteolin minimized the production of ROS, enhanced the Nrf2 and heme oxygenase‐1 (HO‐1) levels; reduced the oxidative damages and inflammation which is crucial to maintain heart functioning under these conditions." (PMID 39830909, 2025). "Moreover, knockdown of HMOX1 ameliorates ferroptosis, thereby alleviating diabetic cardiomyopathy by reducing cardiac fibrosis and improving cardiac function." (PMID 40235314, 2025). "In the results, firstly, compared with control rats, myocardial cell size, left ventricular mass index, and myocardial apoptosis index were increased, miR-503 was increased, and Nrf2, malondialdehyde (MDA), and heme oxygenase 1 (HO-1) were decreased in diabetic cardiomyopathy rats." (PMID 29404371, 2017). "In diabetic cardiomyopathy (DCM), lysine acetyltransferase 2a (Kat2a) triggers ferroptosis by enhancing histone acetylation at the promoter regions of TfR1 and Hmox1, unveiling a previously unrecognized role of the Kat2a/Hmox1/TfR1 signaling axis." (PMID 41550269, 2026).
emphysema (30 papers, 2008 to 2025). "Previous studies have shown that deficiency of Nrf2 or HMOX1 increases susceptibility to CS-induced emphysema, and increases lung cell apoptosis and inflammation." (PMID 36670877, 2022). "Previous studies have shown that the genetic ablation of Nrf2 or HMOX1 enhances susceptibility to CSE-induced emphysema, and increases lung cell apoptosis." (PMID 36670877, 2022). "The (GT)n polymorphism in the HMOX1 gene was investigated in a Japanese study population and the L class of alleles (≥ 33 repeats) was significantly associated with pulmonary emphysema in smokers." (PMID 21902835, 2011). "Irisin and physical exercise have been confirmed to exert a mitigating effect on emphysema induced by cigarette smoking, an effect mediated via the Nrf2/heme oxygenase 1 (HO-1) pathway." (PMID 40862708, 2025). "Exercise and irisin ameliorate cigarette-induced emphysema, and this effect is through the Nrf2/heme oxygenase 1 (HO-1) pathway." (PMID 38143500, 2023). "HMOX1, belongs to the heme oxygenase isoforms, was reported to have the ability of protecting against airway inflammation and emphysema." (PMID 35721789, 2022). "HMOX1 is cytoprotective against CS and required to protect against cadmium-induced emphysema." (PMID 30626320, 2019). "Finally, overexpression of HMOX-1 in mouse lungs was shown to suppress elastase-induced emphysema by attenuating neutrophilic inflammation." (PMID 20920189, 2010). "Among these, HMOX1 or HO‐1, the inducible isoform responding to various stimuli in the environment, was confirmed to play a pivotal role in protecting against mucus hypersecretion 8, emphysema 9, 10, 11, airway inflammation 12, which were the main characteristics of COPD, in a series of studies." (PMID 27998018, 2017).
diabetic retinopathy (29 papers, 2014 to 2026). "In conclusion, ACE, HMOX1, and ACE have been identified as promising potential diagnostic biomarkers associated with nucleotide metabolism in diabetic retinopathy." (PMID 40282274, 2025). "Studies have certified that quercetin can protect the nerves in diabetic rat retina and prevent diabetic retinopathy in rats by inducing heme oxygenase-1 expression." (PMID 35024051, 2022). "Nrf2 is also an important regulator of oxidative-stress-related protein, including heme oxygenase-1, and it plays a central role in the protection against oxidative and apoptotic damage in diabetic retinopathy." (PMID 32899874, 2020). "The hub genes HMOX1 and PTGS2, and their associated transcription factors and miRNAs, may be involved in ferroptosis in diabetic retinopathy." (PMID 36689408, 2023). "Further analysis involving PPI network construction and multiple algorithms identified HMOX1, TLR4, and ACE as biomarkers of diabetic retinopathy." (PMID 40282274, 2025). "Although we have identified the critical roles of HMOX1, TLR4, and ACE in diabetic retinopathy through bioinformatics analysis and experimental validation, this study still has several limitations." (PMID 40282274, 2025). "In conclusion, we found that HMOX1 and PTGS2 are hub genes involved in ferroptosis process of diabetic retinopathy." (PMID 36689408, 2023). "Previous studies have also recognized HMOX1 and TLR4 as diabetic retinopathy biomarkers." (PMID 40282274, 2025). "Additionally, the protein expressions of heme oxygenase‐1 (HO‐1), glutamate‐cysteine ligase catalytic subunit (GCLC), and NAD(P)H dehydrogenase (quinone 1) (NQO1) were all significantly reduced in mice with diabetic retinopathy, and all were significantly restored by the supplement of GSP." (PMID 41409191, 2025).
inflammatory bowel disease (29 papers, 2010 to 2026). A spectrum of small and large bowel inflammatory diseases of unknown etiology. "Inflammatory Bowel Diseases, which includes Crohn's Disease (CD) and Ulcerative Colitis (UC), are one of the most studied ailments associated to HMOX1 effects." (PMID 30258436, 2018). "Hmox1 has been identified as a promising target for inflammatory bowel disease treatment due to its modulating effects on the immune response." (PMID 36077344, 2022).
multiple myeloma (29 papers, 2014 to 2025). "Logistic regression and ROC analysis showed that BDNF in CD4+ T cells and heme oxygenase 1 in monocytes significantly distinguished between patients with myeloma versus patients with AL amyloidosis (AUC = 0.75)." (PMID 40977494, 2025). "We found that carfilzomib upregulated the expression of several genes related to UPR, such as HSPA6 (heat shock protein family A (Hsp70) member 6) and HMOX1 (hemo oxygenase 1), in myeloma cell lines." (PMID 37895838, 2023). "The relationship between the expression levels of HSPA6 or HMOX1 genes and prognosis of myeloma patients treated with proteasome inhibitors was assessed using gene expression data and clinical information obtained from the public database (GSE9782)." (PMID 37895838, 2023). "The addition of phorbol 12‐myristate 13‐acetate (PMA), a ROS inducer, significantly increased HMOX1/HMOX1 in myeloma cells." (PMID 36775962, 2023). "We found that carfilzomib upregulated the expression of several genes related to UPR, including HSPA6 and HMOX1, in myeloma cell lines." (PMID 37895838, 2023). "In the same year Raninga and colleagues investigated a possible crosstalk between TrxR and heme oxygenase‐1 (HO‐1) in multiple myeloma cell lines RPMI8226, U266, and OPM2, aiming to demonstrate the need to target multiple antioxidant systems." (PMID 34850406, 2022). "The involvement of HMOX1 in myeloma cells has been reported in several studies." (PMID 36775962, 2023). "As HMOX1 can reduce ROS, providing excessive ROS may be a possible therapeutic strategy for adapting myeloma cells to hypoxia." (PMID 36775962, 2023). "However, although HMOX1 expression is induced by hypoxia, the critical function of HMOX1 in myeloma cells adapted to a hypoxic microenvironment remains unclear." (PMID 36775962, 2023). "High expression of both HMOX1 and HSPA6 correlated positively with overall survival of myeloma patients." (PMID 37895838, 2023). "Interestingly, hypoxic stimulation increased MAFB/MafB expression in myeloma cells; in addition, the knockdown of MAFB under hypoxic conditions suppressed HMOX1 expression." (PMID 36775962, 2023). "We found that even in the absence of translocation, hypoxic stress increased the expression of MAFB/MafB, which is a poor prognostic factor in myeloma, and that MAFB may be involved in HMOX1 expression." (PMID 36775962, 2023). "LMK235 at concentrations of 1–5 μM showed potent antimyeloma activity and downregulated heme oxygenase-1, which is an NFE2L2 transcription factor-regulated gene that may be a potential target for chemoresistant multiple myeloma treatment." (PMID 36139696, 2022). "In addition, our microarray data showed that myeloma patient samples exposed to hypoxia had high expression of HMOX1 but not of the isozyme HMOX2." (PMID 36775962, 2023).
renal carcinoma (29 papers, 2010 to 2026). A carcinoma arising from the epithelium of the renal parenchyma or the renal pelvis. "SLC7A11 and HMOX1 were found to be upregulated in renal cancer tissues, while MT1G was downregulated." (PMID 38609844, 2024). "Three genes (SLC7A11, HMOX1, and MT1G) were identified as differentially expressed genes (DEGs) associated with renal cancer prognosis using survival analysis screening." (PMID 38609844, 2024). "The survival analysis screening resulted in three DEGs associated with renal cancer prognosis, namely SLC7A11, HMOX1, and MT1G." (PMID 35360452, 2021). "Specifically, SLC7A11 and HMOX1 were upregulated in renal cancer tissues, while MT1G was downregulated." (PMID 35360452, 2021). "Survival analysis was performed on the whole renal cancer samples in TCGA, and high expression of SLC7A11, HMOX1 and MT1G all presented some prognostic risk." (PMID 35360452, 2021). "We have recently demonstrated that the induction of c-Met promotes over-expression of the cytoprotective molecule heme oxygenase-1 (HO-1) for the survival of renal cancer cells." (PMID 28724911, 2017). "Using protein chip technology and small interfering RNA (siRNA), they discovered that high expression of CXCR3-B significantly downregulated the expression of heme oxygenase-1 (HO-1), an anti-apoptotic protein, and that inhibiting HO-1 expression enhanced renal cancer cell apoptosis." (PMID 40786052, 2025). "Moreover, an investigation focused on how c-Met-mediated signaling, via binding to HGF, modulates apoptosis and immune escape mechanisms in renal cancer cells by regulating novel molecules heme oxygenase-1 (HO-1) and PD-L1." (PMID 39664377, 2024). "Previous studies demonstrated that HMOX1 (heme oxygenase-1), a well-known antioxidant enzyme, could promote the ferroptosis of tumor cells in breast and renal cancers by involving in iron supplement and lipid peroxidation." (PMID 36313179, 2022). "In summary, we systematically addressed the prognostic ability of SLC7A11, HMOX1, and MT1G in overall renal cancer and different renal cancer subtypes in this study." (PMID 35360452, 2021). "It has been reported that the cytoprotective enzyme heme oxygenase-1(HO-1) down-regulated autophagy-related proteins Beclin-1 and LC3B-II in renal cancer cells." (PMID 33643028, 2020). "In human renal cancer cell lines (786-0 and Caki-1), honokiol induced down-regulation of the expression of VEGF and heme oxygenase-1 (HO-1) via the Ras signalling pathway thus inhibit angiogenesis." (PMID 31877856, 2019). "Nevertheless, we found that the high level of expression of HMOX1 was no longer a poor prognostic factor in various subtypes of renal cancer, and its assessment for the poor prognosis of KICH did not seem to be more accurate." (PMID 35360452, 2021). "We, therefore, speculate that high HMOX1 expression does not serve as a poor prognostic factor for overall renal cancer patients due to the high heterogeneity among different subtypes of renal cancer." (PMID 35360452, 2021).
acute pancreatitis (28 papers, 2017 to 2026). An acute inflammatory process that leads to necrosis of the pancreatic parenchyma. "Notably, Sesn2, Kras, Hmox1, and Nfe2l2 exhibited significant expression differences during acute pancreatitis, suggesting they may serve as potential biomarkers for the condition." (PMID 41894401, 2026).
bladder cancer (28 papers, 2013 to 2025). "Similarly, WFA upregulates the mRNA expression of antioxidant genes (NFE2L2, CAT, SOD1, TXN, GSR, NQO1, and HMOX1) in bladder cancer cells associated with oxidative stress generation." (PMID 34209212, 2021). "Previous studies have shown that the expression of HMOX1 is promoted by the anti-tumoral drug curcumin in colon, prostate, breast and bladder cancers." (PMID 29560114, 2018). "A urinary bladder cancer study found GCLC, GCLM, HMOX1, and NQO1 to be upregulated." (PMID 41109135, 2025). "Similarly, PDT with hypericin in human bladder carcinoma cells resulted in elevated expression of nuclear NRF2 protein and heme oxygenase-1 (HO-1) through p38MAPK and PI3K pathways." (PMID 25226504, 2014). "In contrast to our previous findings, TalaA-triggered ferroptosis of bladder cancer cells does not occur through the inhibition of SLC7A11 expression but rather through the upregulation of transferrin and heme oxygenase 1 in bladder cancer cells." (PMID 37866481, 2023).
multiple sclerosis (27 papers, 2009 to 2025). A progressive autoimmune disorder affecting the central nervous system resulting in demyelination. "Twenty-five additional PubMed publications (from OmniCorp) supported an association between carbon monoxide and multiple sclerosis, with several suggesting the involvement of heme oxygenase-1, which is described as an enzyme that oxidizes heme to bilirubin and carbon monoxide." (PMID 34283031, 2021). "It has been observed that multiple sclerosis patients show a decreased expression of HMOX1 in mononuclear cells from the peripheral blood during disease exacerbation, similar to SLE patients." (PMID 30258436, 2018). "A recent study has suggested an association between HMOX1 and HMOX2 polymorphisms and the risk of developing multiple sclerosis in Spanish Caucasian men." (PMID 30258436, 2018). "However, more recent evidence suggests that a chronic heme oxygenase-1 response in glial cells may promote neurodegeneration and thereby exacerbate multiple sclerosis and other neurodegenerative diseases." (PMID 34283031, 2021). "Moreover, several studies support the notion that HMOX1 overexpression in the brain and spinal cord of multiple sclerosis patients could play an important role in multiple sclerosis patients, which was also observed in the experimental autoimmune encephalomyelitis (EAE) model." (PMID 30258436, 2018).
vitiligo (27 papers, 2013 to 2025). Generalized well circumscribed patches of leukoderma that are generally distributed over symmetric body locations and is due to autoimmune destruction of melanocytes. "Several experiments illustrated the destruction of nuclear factor E2-related factor 2-antioxidant response element/heme oxygenase-1 (Nrf2-ARE/HO-1) pathway in melanocytes and keratinocytes in vitiligo, which will be further described in the following chapters." (PMID 35103096, 2022). "In vitiligo, melanocytes show poor antioxidant capacity due to alterations in antioxidant mechanisms, such as AHR and NRF2/ heme oxygenase-1(HO-1) system, which result in high levels of superoxide dismutase and low levels of catalase." (PMID 36551332, 2022). "In vitiligo, inactive Nrf2 signaling is ineffective in protecting HEM from H2O2-induced OS damage and, therefore, rarely prevents melanocyte apoptosis by mediating its downstream antioxidant gene heme oxygenase-1 (HO-1)." (PMID 36439174, 2022). "The nuclear factor E2 related to factor 2-antioxidant/heme oxygenase 1 response element (Nrf2-ARE/HO-1), a key metabolic pathway for genetic signaling transduction of enzymes related to the antioxidant system, is impaired in vitiligo patients." (PMID 35360245, 2022). "In vitiligo, inactive Nrf2 signal was inefficient to protect human melanocytes from H2O2-induced OS damage and thus seldom stopped melanocytes apoptosis via mediating its downstream antioxidant gene heme oxygenase-1 (HO-1)." (PMID 34355664, 2021).
acute respiratory distress syndrome (26 papers, 2008 to 2025). Progressive and life-threatening pulmonary distress in the absence of an underlying pulmonary condition, usually following major trauma or surgery. "HMOX1 (GT)n ≥ 30 alleles have recently been described in association with severity of acute respiratory distress syndrome (ARDS), and with potential significance in the outcome of SARS-CoV2 infection." (PMID 35326205, 2022). "In humans, the genotypes of a heme oxygenase-1 polymorphism in adult respiratory distress syndrome are associated with outcome." (PMID 22800762, 2012). "Here, we investigated whether the degree of oxidative stress as indicated by serum heme oxygenase-1 (HO-1) is clinically useful for predicting prognosis among the patients with acute respiratory distress syndrome (ARDS) and acute exacerbation of interstitial lung disease (AE-ILD)." (PMID 33238962, 2020).
chronic kidney disease (26 papers, 2010 to 2025). Impairment of the renal function secondary to chronic kidney damage persisting for three or more months. "In addition, genetic variations in two coding regions of Apolipoprotein L1 (APOL1) and Heme oxygenase 1 (HMOX1) genes have been associated to chronic kidney disease, and to SCD nephropathy." (PMID 33790942, 2021). "In view of its potent antioxidative effect, tripterine has been demonstrated to significantly alleviate oxidative stress and vascular calcification in chronic kidney disease by up-regulating heme oxygenase-1 (HO-1)." (PMID 40799529, 2025). "However, other studies have found that HMOX1 can inhibit the calcification of human VICs in vitro, and the up-regulation of HMOX1 can relieve oxidative stress and vascular calcification in chronic kidney disease." (PMID 37491214, 2023).